ACTL6A (actin like 6A)
Diseases named in the same sentence as ACTL6A in open-access papers (continued):
Sharing a sentence is not in itself a finding about the gene and the disease.
cancer (42 papers, 2008 to 2025). A tumor composed of atypical neoplastic, often pleomorphic cells that invade other tissues. "Actin-like protein 6A (ACTL6A) is thought to be associated with the survival and prognosis of patients with a variety of human cancers." (PMID 41137713, 2025). "Discussion: ACTL6A emerges as a promising diagnostic and therapeutic target in cancer, with implications for prognosis and therapy." (PMID 38872915, 2024). "A functional role for p21Cip1 was confirmed by showing that suppressing p21Cip1 level in ACTL6A knockdown or knockout cells, attenuates the anti-cancer response associated with ACTL6A loss." (PMID 34689163, 2021). "Although ACTL6A was characterized as an oncogenic driver in many human cancers, the underlying mechanisms remain limited." (PMID 33541412, 2021). "Although ACTL6A has been characterized as an oncogene in many human cancers, its role in GC is unknown, and knowledge of the underlying mechanisms is limited." (PMID 37443154, 2023). "Thus, ACTL6A loss results in increased p21Cip1 levels and this is associated with an attenuated cancer phenotype." (PMID 34689163, 2021). "Moreover, elevated p21Cip1 is required to suppress the cancer phenotype, as the phenotype persists when the p21Cip1 increase is inhibited in ACTL6A deficient cells." (PMID 34689163, 2021). "Increased Actin-like 6A (ACTL6A) expression has been implicated in the development of diverse cancers and recently associated with the Hippo signaling pathway, which is known to regulate biological properties, including proliferation, tissue regeneration, stem cell biology, as well as tumorigenesis." (PMID 29725063, 2018). "Mechanistic heterogeneity: How does ACTL6A achieve divergent functions (e.g., pro-survival vs. pro-metastatic) in different cancer types?" (PMID 40657395, 2025). "FBXW7 reduces ACTL6A protein half-life through ubiquitination-mediated degradation, significantly inhibiting cancer stem cell properties." (PMID 40657395, 2025). "The study of ACTL6A across cancer types highlights its crucial function as an oncogene in multiple malignancies." (PMID 40657395, 2025). "By bridging mechanistic insights with translational challenges, this work aims to redefine ACTL6A as a linchpin of cancer adaptability and provide a roadmap for precision oncology strategies." (PMID 40657395, 2025). "As a key chromatin remodeling factor, ACTL6A plays a crucial role in the development and progression of various cancers." (PMID 40657395, 2025). "ACTL6A plays a crucial role in several types of cancer, making it a promising target for therapeutic strategies." (PMID 40657395, 2025). "This integrative approach enhances our understanding of ACTL6A's role in cancer pathogenesis and treatment." (PMID 38872915, 2024). "ACTL6A is highly expressed in several cancers and acts as a driver of cancer cell survival, differentiation, migration, and metastasis." (PMID 39502735, 2024). "One study identified a role of ACTL6A in repairing cisplatin-induced DNA damage seen in cancer therapeutic resistance." (PMID 38914477, 2024). "First, analysis of mRNA expression data obtained from the GC datasets GSE13911, GSE27342, GSE13861 in the Gene Expression Omnibus (GEO) demonstrated that the ACTL6A expression level was higher in cancer tissues than in normal tissues." (PMID 37443154, 2023). "Mutations in Arp module subunits, ACTB and ACTL6A/B, were nearly selectively enriched in NDDs, whereas mutations in the helicase domain of SMARCA4 were more enriched in cancer." (PMID 37500730, 2023). "ACTL6A has been reported to drive cancer progression by stabilizing the YAP1/TAZ pro-cancer transcriptional regulators, and by suppressing expression of the p21Cip1 cyclin-dependent kinase inhibitor." (PMID 34689163, 2021).
cancer (continued). "Our study provides the role of ACTL6A in cervical oncogenesis and reveals a potential target for therapeutic intervention in this cancer type." (PMID 34395295, 2021). "In contrast, some studies have reported that ACTL6A amplification and overexpression are common events in cancers." (PMID 34395295, 2021). "To understand the relationship between ACTL6A and p21Cip1 level, and the cancer cell phenotype, we treated cells with combinations of ACTL6A- and p21Cip1-siRNA and monitored the impact on cell invasion." (PMID 34689163, 2021). "Actin-Like Protein 6A (ACTL6A, BAF53a) is a SWI/SNF regulatory complex protein that is elevated in cancer cells and has been implicated as a driver of cancer cell survival and tumor formation." (PMID 34689163, 2021). "As a novel oncogene, ACTL6A is aberrantly amplified in several types of human cancers and has been shown to regulate tumor growth and progression." (PMID 31649264, 2019). "To study how the cancer cells were affected by the genetic alteration of BRD9 or ACTL6A, we performed KEGG analysis and GSEA analysis." (PMID 31504061, 2019). "Increased ACTL6A expression has been reported in various cancers, including primary rhabdomyosarcomas, hepatocellular carcinoma, and osteosarcoma." (PMID 29725063, 2018). "It suggests the importance of ACTL6A for the survival of HPDE cancer cell line and indicates its importance as a therapeutic target." (PMID 26777304, 2016). "Utilizing advanced biotechnological and drug design approaches is crucial for creating targeted and safe drugs focusing on ACTL6A, which could provide new therapeutic opportunities for cancer patients." (PMID 40657395, 2025). "Similarly, siRNA- and shRNA-transfected HNC cell lines have shown promising results for downregulating ACTL6A expressions; these findings offer hope for tackling chemoresistance in cancer therapy." (PMID 40510426, 2025). "Machine learning models demonstrated ACTL6A's potential for cancer detection." (PMID 38872915, 2024). "Moreover, preventing the increase in p21Cip1 in ACTL6A knockdown cells (using p21Cip1-siRNA) partially restores cell invasion, suggesting that the increase in p21Cip1 is responsible for suppression of the cancer phenotype in ACTL6A knockdown cells." (PMID 34689163, 2021). "Previously, focal amplifications of BRD9 and ACTL6A have been identified and their overexpression may correlate with unfavorable clinical outcomes in a set of cancers." (PMID 34598711, 2021). "To understand the mechanism of action, we show that p21Cip1 level is suppressed in ACTL6A competent cells and is increased in ACTL6A knockout cells, suggesting that ACTL6A may maintain the cancer phenotype by suppressing p21Cip1 expression." (PMID 34689163, 2021). "ACTL6A has been reported to maintain an aggressive phenotype in cancer cells." (PMID 34689163, 2021). "In addition, ACTL6A stabilizes the YAP1/TAZ pro-cancer transcriptional regulators, which are part of the Hippo signaling cascade, and reduces expression of the p21Cip1 tumor suppressor." (PMID 34689163, 2021). "Studies have revealed that ACTL6A is oncogenic in human cancer." (PMID 31504061, 2019). "Several studies demonstrated that ACTL6A is amplified and upregulated in different cancers." (PMID 31769422, 2019). "Among them, BRD9 and ACTL6A showed a high amplification frequency across multiple cancers." (PMID 31504061, 2019). "Above all, we first indicated the common amplification of BRD9 and ACTL6A in cancers, which could be regarded as potential treatment targets in the future." (PMID 31504061, 2019). "It has been reported that ACTL6A plays critical roles in varied cancer phenotypes." (PMID 31649264, 2019).
cancer (continued). "According to these studies, we could strongly suggest that ACTL6A would play a pan-oncogenic role in cancer invasion and metastasis." (PMID 30348114, 2018). "Therefore, this study further verified the EMT activating role of ACTL6A, which expanded the understanding of the biological role of ACTL6A in cancer invasion and metastasis." (PMID 30348114, 2018). "As a central component of chromatin remodeling complexes, ACTL6A is involved in numerous biological processes, including chromatin remodeling, gene expression regulation, stem cell maintenance, cellular differentiation, embryonic development, DNA repair, and cancer." (PMID 40657395, 2025). "Moreover, ACTL6A promoted HCC cancer stem cell‐like properties and tumorigenic abilities." (PMID 39502735, 2024). "Moreover, ACTL6A knockdown resulted in an increase in p21Cip1 and an attenuated cancer phenotype." (PMID 34689163, 2021). "Taken all these researches, we could conclude that ACTL6A was closely connected with EMT in cancer." (PMID 30348114, 2018). "Together, these studies highlight the potential of ACTL6A as a key regulator in the development and progression of RMS and NSCLC, making it an attractive target for therapeutic intervention in these cancers." (PMID 40657395, 2025). "Previous studies demonstrated that ACTL6A controls the epithelial‐mesenchymal transition (EMT) progress in HCC cells and facilitates the invasive and migrative abilities of cancer cells." (PMID 39502735, 2024). "Especially, 7 of ATPCRs showed a significant overexpression in multiple cancer types, including TTF2 (n = 6), RAD54L (n = 4), ACTL6A (n = 4), CHD7 (n = 3), HELLS (n = 3), HLTF (n = 3), and ACTR5 (n = 3)." (PMID 35789070, 2022). "ACTL6A, CHD2, and ACTB had the highest pan‐cancer G‐score for amplification, whereas CHD5, SHPRH, INO80, and ACTR8 had the highest pan‐cancer G‐score for deletions." (PMID 35789070, 2022). "An important example is Actin-Like Protein 6A (ACTL6A), which is part of the SWI/SNF complex, but also acts independently to drive cancer cell survival." (PMID 34689163, 2021). "SWI/SNF complex subunit Actin-like protein 6A (ACTL6A) has been regarded as an oncogene, regulating the proliferation, migration and invasion of cancer cells." (PMID 34395295, 2021). "Specifically, ACTL6A, SMARCD1, SMARCA4 and BRD9 are among the top upregulated genes in cancers compared with the paired control samples." (PMID 34598711, 2021). "Multiple actin-related proteins including ARPC1B, ARPC5, ACTL6A, and CFL1, which are markers for aggressive cancers, were part of the upregulated network nodes." (PMID 33317623, 2020). "Moreover, ACTL6A is associated with stem cell maintenance, including activation of the Hippo-YAP pathway, Nanog binding to pluripotency genes, and repression of differentiation genes, which might explain its role in cancer." (PMID 31769422, 2019). "In this study, we discovered a universal comutation relationship between ACTL6A and TP63 across almost 25 cancers (p<0.001, log odds ratio>3)." (PMID 31504061, 2019). "Of the close to 250 genes located at the 3q26-29 amplicon, we find that ACTL6A and FXR1 are among the 10 and 30 most frequently overexpressed genes in this cancer type, respectively." (PMID 25484917, 2014). "ACTL6A functions as a key component of chromatin remodeling complexes, including SWI/SNF, INO80, and NuA4/TIP60, while also exerting independent oncogenic effects by promoting cancer cell stemness, invasion, and metastasis." (PMID 40657395, 2025). "Current reviews on ACTL6A focus narrowly on its role in chromatin remodeling, lacking integration of multi-omics data and cross-cancer analyses." (PMID 40657395, 2025). "Different from the previous reports, the novel oncogenic functions of ACTL6A was investigated in TNBC cell lines, suggesting it may be distinct regulation in human cancers." (PMID 33541412, 2021).
cancer (continued). "A key role of p21Cip1 was confirmed by showing that p21Cip1 knockdown results in increased cancer cell invasion and migration thereby confirming that the increase in p21Cip1 in ACTL6A negative cells suppresses the cancer phenotype." (PMID 34689163, 2021). "According to the result, ACTL6A is “common essential” for at least 90% cancer lines, however, there is still no any druggable structure of ACTL6A reported." (PMID 31504061, 2019). "In addition, based on the clinical data, the overexpression of ACTL6A and BRD9 reduced the survival time of patients in a set of cancers." (PMID 31504061, 2019). "As ACTL6A promotes a stem-cell-like state, it is not surprising that its levels are increased in cancer." (PMID 31769422, 2019). "Additionally, ACTL6A and BRD9 showed a border spectrum of genetic alterations in five different cancer types." (PMID 31504061, 2019). "Additionally, the bioinformatics analyses were performed for two significantly amplified genes, ACTL6A and BRD9, to investigate their oncogenic roles in human cancers." (PMID 31504061, 2019). "The results showed that the ACTL6A mRNA expression level was higher in cancer tissues than in noncancerous tissues (P < 0.01)." (PMID 30348114, 2018). "Although the result of immunofluorescence indicated that the protein levels are high in cancers, whether the protein levels are increased with the amplification of the copy number of ACTL6A or BRD9 is still not clear (p value>0.05)." (PMID 31504061, 2019). "To determine whether the increased copy number of ACTL6A and BRD9 led to an increase in their expression levels, we acquired two pan-cancer boxplots regarding the difference of these two genes expression between normal and tumor tissues from Tumor IMmune Estimation Resource (Timer)." (PMID 31504061, 2019). "ACTL6B, a paralog of ACTL6A, has not been studied extensively in cancer." (PMID 31769422, 2019). "Therefore, compared to ACTL6A, BRD9 could be a better choice for us to develop the treatment of cancers." (PMID 31504061, 2019). "We analysed ACTL6A, BRG1, BRM and loricrin expression at the mRNA level in normal and in cancer tissues." (PMID 35201472, 2021). "Therefore, at least in these cancer types, the protein levels of both BRD9 and ACTL6A are increased with the increase of mRNA, and there is no any altered translocation has been discovered so far." (PMID 31504061, 2019).
tumor (33 papers, 2014 to 2025). "Biochemical analysis of tumor extracts confirms ACTL6A knockout and shows that this is associated with increased levels of p21Cip1." (PMID 34689163, 2021). "Wild-type Meso-1 cells and ACTL6A knockout cells (Meso1-ACtL6A-KOc1-5-1) cells were injected into immunocompromised mice to monitor the impact of ACTL6A loss on tumor formation." (PMID 34689163, 2021). "Conversely, ACTL6A loss reduces cell proliferation and tumor growth." (PMID 40877226, 2025). "This study identifies ACTL6A as a key regulator of aerobic glycolysis and hypoxic cell growth in HNSCC, defines a novel association between ACTL6A expression and AP-1 signaling, and establishes a synthetic lethality strategy to drive tumor killing in a treatment resistant HNSCC cell line." (PMID 40950224, 2025). "Detailed studies of ACTL6A's mechanisms across different tumor types may lead to new diagnostic and therapeutic strategies." (PMID 40657395, 2025). "In addition, ACTL6A knockout markedly reduces tumor formation and this is associated with elevated tumor levels of p21Cip1." (PMID 34689163, 2021). "We found that ACTL6A knockdown caused the decrease of tumor weight vs. control group." (PMID 31649264, 2019). "A mouse xenograft model with HCT116 cells harboring ACTL6A-targeting shRNA was established to explore the role of ACTL6A in tumor growth in vivo." (PMID 40877226, 2025). "Rescue experiments confirmed that restoring ACTL6A expression or reactivating YAP signaling abrogates miR-216a-3p-mediated tumor suppression, establishing a functional axis: miR-216a-3p→ACTL6A→YAP." (PMID 40657395, 2025). "Future research should clarify the specific mechanisms of ACTL6A in various tumor types and investigate its interactions with other molecular markers." (PMID 40657395, 2025). "Doxycycline (DOX)-induced ACTL6A knockdown substantially reduced tumor volume, indicating the inhibitory effect of ACTL6A depletion on tumor growth." (PMID 40877226, 2025). "Clinically, ACTL6A overexpression correlates with advanced tumor stage, therapy resistance, and poor prognosis, positioning it as a promising prognostic biomarker and therapeutic target." (PMID 40657395, 2025). "ACTL6A contributes to CRC cell proliferation by inhibiting the KLF4-mediated transcriptional activation of tumor-suppressive genes." (PMID 40877226, 2025). "We specifically focused on repair-related genes, exemplified by ACTL6A, a gene proven to promote the repair of cisplatin-induced DNA damage in tumor therapy." (PMID 38935071, 2024). "The impact of ACTL6A on immune cell infiltration in the tumor microenvironment was evaluated, along with molecular docking studies and machine learning models." (PMID 38872915, 2024). "To determine the in vivo functional contribution of ACTL6A to tumor progress, we performed GC xenograft mouse model experiments." (PMID 37443154, 2023). "Knocking down ACTL6A expression with shACTL6A significantly reduced tumor growth, and NAC treatment (intraperitoneal (i.p.)injection, 200 mg/kg/day) significantly reversed this effect." (PMID 37443154, 2023). "To assess the biological relevance of these findings, we tested the impact of ACTL6A knockout on tumor formation." (PMID 34689163, 2021). "The fact that ACTL6A knockout leads to increased p21Cip1 levels and reduced tumor growth argues that ACTL6A suppresses p21Cip1 to maintain aggressive tumor growth." (PMID 34689163, 2021). "ACTL6A overexpression promoted, while silencing ACTL6A suppressed cell proliferation and tumor growth in TNBC cells in vitro and in vivo, which was dependent on MYC signaling." (PMID 33541412, 2021). "We evaluated uc.291/ACTL6A/BRG1 expression at mRNA level in a cohort of 39 human tumour specimens as well as the expression at protein level by tissue microarray (TMA)." (PMID 35201472, 2021). "Mechanistic data revealed that ACTL6A promoted tumor growth and cell cycle progress by regulating c-Myc activity." (PMID 34395295, 2021).